PDCD10 (programmed cell death 10)
Description:
Promotes cell proliferation. Modulates apoptotic pathways. Increases mitogen-activated protein kinase activity and STK26 activity. Important for cell migration, and for normal structure and assembly of the Golgi complex. Part of the striatin-interacting phosphatase and kinase (STRIPAK) complexes. STRIPAK complexes have critical roles in protein (de)phosphorylation and are regulators of multiple signaling pathways including Hippo, MAPK, nuclear receptor and cytoskeleton remodeling. Different types of STRIPAK complexes are involved in a variety of biological processes such as cell growth, differentiation, apoptosis, metabolism and immune regulation. Important for KDR/VEGFR2 signaling. Increases the stability of KDR/VEGFR2 and prevents its breakdown. Required for normal cardiovascular development. Required for normal angiogenesis, vasculogenesis and hematopoiesis during embryonic development (By similarity).
Synonyms: CCM3; TFAR15
Tractability: Small molecule: it has a binding pocket of medium quality. Antibody: UniProt places it where antibodies can reach, with medium confidence; its Gene Ontology location is reachable by antibodies, with medium confidence. PROTAC: UniProt records ubiquitination sites on it; ubiquitination databases record sites on it; its protein half-life has been measured.
Gene: Protein-coding gene on chromosome 3 (167,683,298 to 167,735,039, reverse strand). Ensembl gene ENSG00000114209.
Subcellular location: Cytoplasm; Golgi apparatus membrane; Cell membrane
Gene Ontology:
Molecular function: protein binding; protein homodimerization activity; protein kinase binding
Biological process: establishment of Golgi localization; Golgi reassembly; intracellular signal transduction; intrinsic apoptotic signaling pathway in response to hydrogen peroxide; negative regulation of apoptotic process; negative regulation of blood vessel endothelial cell proliferation involved in sprouting angiogenesis; negative regulation of cell migration involved in sprouting angiogenesis; negative regulation of gene expression; positive regulation of cell migration; positive regulation of cell population proliferation; positive regulation of gene expression; positive regulation of intracellular protein transport; positive regulation of MAP kinase activity; positive regulation of Notch signaling pathway; positive regulation of peptidyl-serine phosphorylation; positive regulation of protein serine/threonine kinase activity; positive regulation of stress-activated MAPK cascade; protein stabilization; regulation of Rho protein signal transduction; stress fiber assembly; wound healing, spreading of cells; endothelium development; regulation of angiogenesis
Cellular component: cytoplasm; cytosol; extracellular exosome; FAR/SIN/STRIPAK complex; Golgi apparatus; Golgi membrane; plasma membrane
Genetic constraint (gnomAD): Loss-of-function variants: 1 observed, 5.12 expected, observed/expected ratio (o/e) 0.2, 90% interval 0.068 to 0.92. That is too few expected variants to judge how well the gene tolerates losing a copy. Missense variants: 32 observed, 42.76 expected, observed/expected ratio (o/e) 0.75, 90% interval 0.56 to 1. Synonymous variants: 8 observed, 13.39 expected, observed/expected ratio (o/e) 0.6, 90% interval 0.35 to 1.08.
Homologues: Orthologues: chimpanzee PDCD10 (100% identical), dog PDCD10 (99% identical), guinea pig PDCD10 (99% identical), macaque PDCD10 (99% identical), mouse Pdcd10 (99% identical), pig PDCD10 (99% identical), rabbit PDCD10 (99% identical), rat Pdcd10 (98% identical), tropical clawed frog pdcd10 (97% identical), zebrafish pdcd10a (93% identical), zebrafish pdcd10b (92% identical), Drosophila melanogaster Ccm3 (48% identical), and 1 more.
Diseases named in the same sentence as PDCD10 in open-access papers:
PDCD10 is named in the same sentence as 84 diseases in open-access papers, as found by Europe PMC text mining. Sharing a sentence is not in itself a finding about the gene and the disease. The quoted sentences say what the papers report.
cerebral cavernous malformation (58 papers, 2007 to 2026). A disorder characterized by malformations in the structure of the capillaries in the brain. "PDCD10 is also known as CCM3, a causative gene of cerebral cavernous malformation, a neurovascular disease characterized by vascular malformations." (PMID 38517886, 2024). "The PDCD10 gene encodes the highly conserved PDCD10 adaptor protein that forms a protein complex with other cerebral cavernous malformation (CCM) disease–associated proteins, KRIT1 and CCM2, in endothelial cells to maintain vessel integrity." (PMID 34156031, 2021). "PDCD10, also known as CCM3, is a gene found to be associated with the human disease cerebral cavernous malformations (CCMs)." (PMID 34156031, 2021). "A loss-of-function mutation in PDCD10 causes the familial form of cerebral cavernous malformation, one of the most common vascular lesions in the central nervous system involving aberrant angiogenesis." (PMID 32850441, 2020). "SPG21 is a negative pro-inflammatory CD4+ cells regulator that can lead to spastic paraplegia while the aberrant PDCD10 expression can be associated with the development of cavernous cerebral malformation." (PMID 28423529, 2017). "Mutations in CCM1 (aka KRIT1), CCM2, or CCM3 (aka PDCD10) gene cause cerebral cavernous malformation in humans." (PMID 27513872, 2016). "Mutations in the genes KRIT1, CCM2, and PDCD10 are known to result in the formation of cerebral cavernous malformations (CCMs)." (PMID 27896269, 2016). "PDCD10 is a recently identified apoptosis‐related gene that has been implicated in mutations associated with cerebral cavernous malformations." (PMID 26647742, 2016). "Mutations in the CCM3/PDCD10 gene (CCM3 from here on) predispose to cerebral cavernous malformations (CCM, OMIM #116860), a common type of vascular malformation which develop almost exclusively in the central nervous system." (PMID 25655101, 2015). "Mutations of PDCD10 predispose to the development of human familial cerebral cavernous malformations (CCM), a brain vascular anomaly involving aberrant angiogenesis and chronic hemorrhage." (PMID 26490252, 2015). "Mutations in the PDCD10 gene cause cerebral cavernous malformations (CCM), a syndrome associated with seizures and neurological deficits due to focal haemorrhages." (PMID 18793432, 2008). "PDCD10 is a gene associated with cerebral cavernous malformation." (PMID 34156031, 2021). "Loss of endothelial PDCD10 affects vascular development and causes cerebral cavernous malformation." (PMID 32850441, 2020). "In cerebral cavernous malformation (CCM), CCM3 (also known as PDCD10) gene mutation promotes the progression of CCM." (PMID 35874764, 2022). "Moreover, much attention has recently been drawn to the study of the PDCD10 function in vessel permeability due to the aggressive hemorrhagic behavior observed in cerebral cavernous malformation patients harboring a PDCD10 mutation and after loss of heterozygosity (LOH) for Pdcd10 in mice." (PMID 26490252, 2015). "Cerebral cavernous malformation (CCM) is a vascular disease caused by mutations in the CCM1/KRIT1, CCM2, or CCM3/PDCD10 genes." (PMID 39402138, 2024). "Mutations in the cerebral cavernous malformation (CCM) genes, KRIT1, CCM2, and PDCD10, cause CCM disease." (PMID 36692953, 2023). "The adaptor protein CCM3 (cerebral cavernous malformation), which directly binds to STRNs via its C-terminal region, was initially recognised as an apoptosis-related gene (PDCD10)." (PMID 38201504, 2023). "The capillary-venous pathology cerebral cavernous malformation (CCM) is caused by loss of CCM1/Krev interaction trapped protein 1 (KRIT1), CCM2/MGC4607, or CCM3/PDCD10 in some endothelial cells." (PMID 37019926, 2023). "Familial forms of the human vascular disease, cerebral cavernous malformation (CCM), arises from mutation in any of three genes (CCM1/KRIT1, CCM2/Malcavernin, and CCM3/PDCD10)." (PMID 36653023, 2023).
cerebral cavernous malformation (continued). "Programmed cell death 10 (PDCD10), originally named TF-1 cell apoptosis related gene 15, is also known as cerebral cavernous malformation 3 (CCM3)." (PMID 34108959, 2021). "Among all the factors influencing the RhoA-ROCK1 signaling, the programmed cell death protein 10 (PDCD10; or cerebral cavernous malformation [CCM] 3) emerges as an upstream regulator." (PMID 30408026, 2018). "We show that TRIM59 regulates the degradation of PDCD10, which is involved in programmed cell death and is the main factor for driving the pathogenesis of the devastating familial cerebral cavernous malformation (CCM) disease." (PMID 30408026, 2018). "Aim of this study is to report additional PDCD10/CCM3 families poorly described so far which account for 10-15% of hereditary cerebral cavernous malformations." (PMID 25354366, 2014). "PDCD10 (CCM3) is involved in cerebral cavernous malformations (CCM) and is found to interact with Ste20-related kinase MST4 to promote cell growth and transformation via modulation of the ERK pathway." (PMID 20015385, 2009). "PDCD10 was recently identified as one of three genes responsible for a heritable form of cerebral cavernous malformations (CCM3) characterized by abnormally enlarged capillary cavities causing seizures and hemorrhages." (PMID 17850668, 2007). "This regulation may impact the proliferation, migration, and angiogenesis of endothelial cells, potentially leading to conditions like Cerebral cavernous malformation (CCM) when PDCD10 is lost in these cells." (PMID 38351531, 2024). "Cerebral cavernous malformations are associated with mutations in three genes: CCM1/KRIT1 (krev interaction trapped-1) (MIM#604214), CCM2/MGC4607 (malcavernin) (MIM#607929), and CCM3/PDCD10 (programmed cell death 10) (MIM#609118)." (PMID 33651268, 2021). "PDCD10 is also known as cerebral cavernous malformation 3 (CCM3)." (PMID 32850441, 2020). "Cerebral cavernous malformations are characterized by the presence of vascular lesions that are most prevalent in the brain and can occur sporadically or through a familial condition from mutations in CCM1/KRIT1, CCM2/Malcavernin, or CCM3/PDCD10 [reviewed in]." (PMID 30181117, 2018). "Cerebral cavernous malformation 3 (CCM3) is also named programmed cell death 10 (PDCD10)." (PMID 28371279, 2017). "In experimental models of cerebral cavernous malformations (CCM), deletion of programmed cell death 10 (CCM3), a molecular regulator of cellular apoptosis, enhances VEGFR3 expression and ERK1/2 activation in LECs, leading to hyperplastic lymphatic development." (PMID 38201272, 2023). "PDCD10, initially deemed as an apoptosis-related gene, controls multiple biological functions, including endothelial cells junctions, cell proliferation and angiogenesis in cerebral cavernous malformation (CCM), cognitive disability, and different types of cancers." (PMID 37781039, 2023). "Loss-of-function mutations are known in one of the three CCM genes: Krev interaction trapped 1 (CCM1/KRIT1), cerebral cavernous malformations 2 (CCM2) and programmed cell death 10 (PDCD10) predisposes to CCMs5,6." (PMID 31796831, 2019). "As the third gene locus related to cerebral cavernous malformations (CCMs), PDCD10 is alternatively named CCM3." (PMID 32450789, 2020). "The set includes images of the control cells (wild-type HUVEC) and cells with knockdown (KD) of the three Cerebral Cavernous Malformation (CCM) proteins, CCM1 (or KRIT1), CCM2, and CCM3 (or PDCD10), which disrupts the integrity of multicellular mesh." (PMID 32881897, 2020). "Programmed cell death 10 (PDCD10) has originally been referred to as TFAR15 (TF-1 cell apoptosis related gene) and is also known as cerebral cavernous malformation 3 (CCM3)." (PMID 26490252, 2015).
breast cancer (20 papers, 2017 to 2024). A primary or metastatic malignant neoplasm involving the breast. "In summary, our study has unveiled TRIM59 as an essential tumor-promoting factor that facilitates breast cancer growth and metastasis through modulating PDCD10-associated signaling pathways, as well as other oncogenic pathways." (PMID 30408026, 2018). "Loss of TRIM59 or PDCD10 suppresses tumor growth both in vitro and in vivo, and the amount of both proteins inversely correlates with survival of breast cancer patients." (PMID 30408026, 2018). "Similarly, loss of PDCD10 also enhanced the chemoresistance of tumor cells in breast cancer and glioma." (PMID 36497468, 2022). "In addition, TRIM59 as an essential tumor-promoting factor that facilitates breast cancer growth and metastasis through modulating PDCD10-associated signaling pathways." (PMID 32867817, 2020). "Conversely, in breast cancer, PDCD10 is downregulated, making cancer cells more resistant to other anti‐cancer drugs, such as doxorubicin, docetaxel, and etoposide." (PMID 38351531, 2024). "In breast cancer, overexpression of PDCD10 induced the inactivation of the ROCK/Rho signal pathway to suppress cell adhesion and promote cell migration and invasion." (PMID 35963638, 2022). "TRIM59 suppresses K63 ubiquitination by RNFT1 and PDCD10 degradation by p62-mediated selective autophagy, which promotes migration of breast cancer cells." (PMID 36202787, 2022). "miR-421/PDCD4, miR-27a-3p/PD-L1, miR-424/PD-L1, miR-26a-5p/PDCD10 and miR-26b-5p/PDCD10 are other routes of participation of miRNAs in the pathogenesis of breast cancer." (PMID 35402235, 2022). "More evidence suggests that PDCD10 acts as an oncogene in some epithelial malignant tumours, such as breast cancer, ovarian cancer, and non-small cell lung cancer." (PMID 34521817, 2021). "Collectively, these findings suggest that TRIM59 promotes breast cancer growth and migration/invasion through PDCD10-induced suppression of ROCK signaling and subsequent MAT." (PMID 30408026, 2018). "Similar to TRIM59, PDCD10 expression was correlated with shortened breast cancer patient survival, suggesting a potential pro-oncogenic role of both TRIM59 and PDCD10 in breast cancer." (PMID 30408026, 2018). "Overall, the deletions of chr13q and chr4p are both early clonal events in the basal PT/PDX panel, highlighting the potential importance of the stoichiometric balance of the PDCD10-GCKIII kinase module as an additional common evolutionary mechanism in this breast cancer subtype." (PMID 38517886, 2024). "However, elevated PDCD10 in ovarian cancer and breast cancer induces more malignant behaviors 41-43." (PMID 37781039, 2023). "Loss of PDCD10 in CAFs drives the activation of CAFs, promotes the nuclear translocation of YAP, and consequently leads to the metastatic dissemination of tumors through extracellular matrix remodeling in mouse models of breast cancer." (PMID 36497468, 2022). "PDCD10 also participates in regulation of stemness of breast cancer cell." (PMID 35963638, 2022). "PDCD10 was identified as the target of miR-200c and overexpression of PDCD10 rescued the oncogenesis inhibited by miR-200c, indicating that PDCD10 exerted a pro-tumorigenic role in breast cancer by maintaining the stemness of tumor stem cells." (PMID 36497468, 2022). "Hence, a therapeutic intervention that interrupts the functional interplays between TRIM59 and PDCD10 might provide a promising strategy to treat breast cancer and CCM." (PMID 30408026, 2018). "Increased PDCD10 has been demonstrated to be able to induce EMT in HCC, breast cancer, prostate cancer, ovarian cancer, and pituitary adenomas." (PMID 36497468, 2022). "Suppression of TRIM59, a highly expressed E3 ligase in breast cancer with metastasis, inhibits metastasis by inducing RNFT1-induced K63 ubiquitination of PDCD10." (PMID 36202787, 2022). "Depletion of PDCD10, STK24, and MST4 in breast cancer cells promotes the generation of the p-ERM arc in lamellipodia." (PMID 34156031, 2021).
breast cancer (continued). "A recent study reported that depletion of TRIM59 suppresses breast cancer metastasis by promoting RNFT1-induced K63 poly ubiquitination and SQSTM1-directed autophagic degradation of PDCD10." (PMID 31600735, 2019). "Bioinformatic analysis and experiments on clinical samples and mouse models of breast cancer unveil a new signaling protein degradation pathway involving TRIM59 and PDCD10 that modulates breast cancer cell growth, survival, and metastasis." (PMID 30408026, 2018). "Tan and colleagues showed that TRIM59 stabilizes the apoptosis-related protein PDCD10 by inhibiting its ubiquitination and subsequent P62-selective autophagic degradation; in turn, this promoted RhoA and ROCK1 activation and metastasis of breast cancer cells." (PMID 33194618, 2020). "We detected the endogenous interaction between RNFT1 and PDCD10 in both breast cancer cell lines but not for IgG controls (IB: RNFT1, lanes 3 versus 1)." (PMID 30408026, 2018). "To test whether PDCD10-ROCK signaling is downstream of TRIM59 but upstream of MLC/ERM to impact breast cancer cells’ contractility, we performed functional rescue experiments by using a ROCK inhibitor (Y-27632) or through the lentivirus-mediated stable expression of PDCD10 in TRIM59 KO MCF7 cells." (PMID 30408026, 2018).
cavernomas (12 papers, 2014 to 2025). "In summary here, the C9 Pdcd10-ko cells in the newly formed Pdcd10-ko specific branch of S0–S2 highly expressed typical cavernoma markers, they were mainly mitotic, and they also had pathological tip cell traits." (PMID 33138917, 2020). "In the corresponding areas of the Pdcd10-ko cerebellum, tip cells were seen at the end of and along pseudo-normal vessels, and also in cavernomas." (PMID 33138917, 2020). "Considering that our group recently reported that cavernomas have clonal origins from expansion of Pdcd10-ko progenitor cells, we investigated the distribution of cells that expressed progenitor cell markers in the STREAM-generated trajectories." (PMID 33138917, 2020). "Cavernous hemangiomas may occur sporadically or be inherited, with the latter associated with loss-of-function mutations in the KRIT1/CCM1, CCM2, or PDCD10/CCM3 genes." (PMID 40963940, 2025). "Cavernomas appear sporadically (1:200) or as an autosomal dominant (1:10,000) loss-of-function germline mutation of KRIT1 (CCM1), Malcavernin (CCM2), or PDCD10 (CCM3) in endothelial cells of the CNS." (PMID 36293431, 2022). "Pdcd10-ko cells of C9 express the same top mitotic phenotype as overt cavernomas." (PMID 33138917, 2020). "However, the tight-junction proteins Claudin-5, and Cingulin, as well as the adherens junction VE-cadherin were not correctly localized at the cell-to-cell contacts in the ECs of the cavernomas of the Pdcd10-ko mice." (PMID 33138917, 2020). "To determine whether the formation of cavernomas occurs for specific subpopulations of ECs, we analyzed the changes in gene expression between the Pdcd10-wt and Pdcd10-ko ECs in each cluster." (PMID 33138917, 2020). "However, considering both pseudo-normal vessels and cavernomas, the densities of the tip cells were similar in the Pdcd10-wt and Pdcd10-ko brains." (PMID 33138917, 2020).